NLRP3 (NLR family pyrin domain containing 3)
Diseases named in the same sentence as NLRP3 in open-access papers (continued):
Sharing a sentence is not in itself a finding about the gene and the disease.
colitis (continued). "Zaki and colleagues showed that mice lacking Nlrp3 are highly susceptible to DSS‐induced colitis, which is consistent with some other reports." (PMID 34705319, 2021). "Previous studies have demonstrated that NLRP3 inflammasome is involved in the pathogenesis of colitis, and targeting NLRP3 inflammasome has been shown to have definite therapeutic effects in a mouse model of colitis." (PMID 33350984, 2021). "Mounting evidence shows that some natural products might affect the severity of colonic inflammation in various colitis models by targeting the NLRP3 inflammasome." (PMID 33808793, 2021). "And combined with the results of molecular docking, the protective effect on DSS-induced experimental colitis might be related to regulation of the NF-κB pathway and NLRP3 inflammasome." (PMID 33859564, 2021). "Moreover, we also noticed that Schisandrin B reduced epithelial cells injury of colitis through regulating pyroptosis by AMPK/Nrf2/NLRP3 inflammasome." (PMID 34628369, 2021). "Thus, the role of bergenin in amelioration of TNBS-colitis in the rat was, at least in part, dependent on its inhibition on the NLRP3/ASC inflammasome." (PMID 33808793, 2021). "In our study, we found that Xi Lei San could significantly inhibit NLRP3 inflammasome activity in rats with DSS-induced colitis and also in TNF-α-induced CACO2 cells." (PMID 33967625, 2021). "As regards colitis, the previous papers assayed higher doses of RA than those used in our study (25–200 mg/kg) and none of them evaluated the effects of RA on the modulation of the NLRP3 inflammasome or the antioxidant signaling pathway Nrf-2/HO-1." (PMID 33530569, 2021). "Therefore, the Nlrp3 inflammasome is critically involved in the maintenance of intestinal homeostasis and protection against colitis." (PMID 35185813, 2021). "It is reported that NLRP3 inflammasome mediated dextran sodium sulfate (DSS)-induced colitis." (PMID 33110394, 2020). "In addition, ginsenoside Rd alleviates DSS-induced colitis pathologies through autophagy/mitophagy-mediated inhibition of the NLRP3 inflammasome." (PMID 32630319, 2020). "There are many reports suggesting that the microbiota activates NLRP3 and exacerbates colitis." (PMID 33143375, 2020). "Different findings point out the hypothesis that a lack in NLRP3 inflammasome components may protect animals from DSS colitis." (PMID 32545788, 2020). "The controversies may be due to various factors, such as differences in genetic backgrounds of mice and humans, compositions of microbiotas, selected models of colitis, and regiospecific features of the NLRP3 inflammasome." (PMID 33143375, 2020). "However, sinapic acid treatment also decreased the serum and colonic levels of IL-1β and IL-18, which were associated with decreased NLRP3, ASC, and caspase-1 protein levels in the colons of colitis mice." (PMID 33312339, 2020). "Furthermore, we unravel a critical role of the canonical NLRP3 inflammasome in Cg-induced IL-1β secretion and colitis, which is an important discovery on the pro-inflammatory properties of this sulfated polysaccharide for pre-clinical studies." (PMID 32894139, 2020). "In vivo, we find GPA peptide could exert anti-inflammatory effects on DSS-induced mice colitis, and its anti-inflammatory effects are abolished in NLRP3-/- mice." (PMID 32950971, 2020). "NLRP3 inflammasome seems to act as a negative modulator of tumorigenesis in colitis-associated cancer, which is confirmatory to the study emphasizing the role of NLRP3 inflammasome in the regulation of intestinal homeostasis and thus protection against colitis." (PMID 32733479, 2020). "Indeed, its link to the NLRP3 inflammasome also validates the role AhR can play in the treatment of colitis in IBD and CAC." (PMID 32456012, 2020). "In addition, the NLRP3 inflammasome was identified as a central mediator of intestinal inflammation in dextran sulfate sodium (DSS)-induced colitis." (PMID 32849554, 2020).
colitis (continued). "Herein, we examine the effect of evodiamine, extracted from the fruit of Evodiae Fructus, on experimental colitis induced by dextran sulfate sodium and exposit whether evodiamine effects on autophagy and NLRP3 inflammasome." (PMID 33240089, 2020). "It is reported that activation of NLRP3 inflammasome plays a critical role in DSS‐induced colitis." (PMID 32945118, 2020). "Finally, we tested the role of NLRP3 inflammasome in a model of Cg-induced colitis, which has been widely used in different species, including rats, mice, rabbits and guinea pigs." (PMID 32894139, 2020). "Finally, we demonstrated in vivo that NLRP3 inflammasome plays a crucial role in Cg-induced colitis in mice." (PMID 32894139, 2020). "Herein, we comprehensively review the literature on inflammasome functioning in the colon and describe the complex interactions of the NLRP3 inflammasome components with inflammatory cytokines, autophagy, and the microbiota in experimental colitis models and patients with IBD." (PMID 33143375, 2020). "Since evodiamine ameliorated colitis injury and inhibited NLRP3 inflammasome, inflammasome and autophagy interacts, we want to know whether evodiamine also act on autophagy." (PMID 33240089, 2020). "However, recent studies have shown the success of NLRP3 inhibitors in ameliorating colitis and in turn CAC, providing strong evidence that an overactivation of NRLP3 is detrimental to intestinal homeostasis." (PMID 32456012, 2020). "Our results demonstrated evodiamine inhibit NLRP3 inflammasome activation via the induction of autophagosome-mediated degradation of inflammasome and the inhibition of NFκB pathway, which synergistically contribute to the effect of evodiamine in colitis." (PMID 33240089, 2020). "NLRP3 has been extensively studied due to its involvement in intestinal disorders such as colitis." (PMID 33182623, 2020). "In summary, GPA ameliorates DSS-induced colitis in a NLRP3-dependent manner." (PMID 32950971, 2020). "In summary, Slco2a1 deficiency increased the PGE2 concentration around macrophages, possibly by suppressing PGE2 metabolism, resulting in activation of the NLRP3 inflammasome in macrophages and thus exacerbating intestinal inflammation in an experimental colitis model." (PMID 32184453, 2020). "However, in stark contrast, other studies has demonstrated that the NLRP3 inflammasome have a protective effect in colitis." (PMID 33603669, 2020). "The studies on the relationship between NLRP3 inflammasome and colitis used different methods to control possible differences in the microbiota composition, such as cohousing, littermate, and embryo transfer; however, some studies did not utilize these controls." (PMID 33143375, 2020). "In our study, we found that GPA peptide, isolated from fish skin gelatin hydrolysate, could ameliorate DSS-induced colitis by targeted inhibition of NLRP3 inflammasome-induced pyroptosis." (PMID 32950971, 2020). "The mechanisms behind the dietary effect of TiO2 on colitis involved NLRP3." (PMID 31109097, 2019). "In addition, GDF11, by inhibiting the NLRP3 inflammasome activation evidenced in vivo and in vitro, ameliorates experimental colitis in mice." (PMID 31248139, 2019). "To examine whether the inflammasome sensor NLRP3 may also be involved in this process, we evaluated the course of colitis in Rag1−/− mice receiving naïve CD4+ T cells sorted from the spleen of Nlrp3−/− mice." (PMID 31379813, 2019). "Considerable evidence supports the idea that NLRP3 inflammasome plays a pro-inflammatory role in colitis pathology, and blockage of IL-1β or IL-18 has been reported to reduce colitis." (PMID 30823406, 2019). "Conversely, loss of Nlrp3 or Caspase-1 expression in CD4+ T cells did not confer a highly colitogenic phenotype in vivo in a T-cell adoptive transfer colitis model." (PMID 31379813, 2019). "On the other hand, E. faecalis cannot prevent DSS-induced colitis in NLRP3 knockout mice." (PMID 30823406, 2019).
colitis (continued). "Indeed, NLRP3 inflammasome-deficient mice, including NLRP3−/−, ASC−/− and Caspase-1−/− mice, were increased highly susceptible to colitis-associated colorectal tumor formation." (PMID 30696442, 2019). "Moreover, induction of the NOD-like receptors family pyrin domain containing 3 (NLRP3) inflammasome by colitis was also significantly inhibited by the IRA." (PMID 31885813, 2019). "Notably, using NLRP3-/- mice, the authors showed that the protective effects of a high-fibre diet against colitis were mediated through NLRP3 activation in colonic epithelial cells." (PMID 31590215, 2019). "By contrast, formation of other colitis-relevant inflammasomes such as AIM2, NLRP6, and NLRC4 by DSS was comparable in colons between control and UVRAGFS-expressing mice, highlighting a critical role of the NLRP3 inflammasome in UVRAGFS-associated colitis." (PMID 31831743, 2019). "Mounting evidence supports the idea that NLRP3 plays a pro-inflammatory role in colitis pathology." (PMID 30823406, 2019). "The NLRP3 inflammasome therefore appears to negatively affect the development of colitis." (PMID 30823406, 2019). "We investigated whether selective pharmacologic blockade of the Nlrp3 inflammasome using MCC950 would reduce the colitis symptoms in Irgm1−/− mice." (PMID 30612879, 2019). "In an attempt to better understand the role of NLRP3 inflammasome in the pathophysiology of bowel inflammation, several studies have investigated the effects of gene deletion and in vivo pharmacological modulation of NLRP3 inflammasome signaling in preclinical models of colitis." (PMID 31200447, 2019). "Furthermore, inhibition of the NLRP3 inflammasome by administration of glyburide, an agent that inhibits ATP-sensitive potassium K+ channels, led to greatly decreased colitis." (PMID 30455704, 2018). "The western blot results of the in vitro experiments showed that treatment with MCC950 significantly reduced the active caspase-1 p10 and IL-1β in BMDMs and colon explants suggesting that MCC950 inhibits the activation of NLRP3 inflammasome in the colitis model." (PMID 29872077, 2018). "Interestingly, pharmacological activation of Rev-erbα by a small molecule (SR9009) protected mice from experimental colitis via a suppressive action on Nlrp3 inflammasome activity." (PMID 30315268, 2018). "Deregulated NLRP3 inflammasome activity, however, contributes to the pathogenesis of a number of human diseases or life-threatening conditions, such as endotoxemia, sepsis, alcoholic liver injury, colitis and acute kidney injury." (PMID 30134814, 2018). "Interestingly, Rev-erbα activation in wild-type mice by SR9009 attenuates DSS-induced colitis, whereas the protective effects are lost in Nlrp3−/− and Rev-erbα−/− mice." (PMID 30315268, 2018). "Therefore, GLP had an anti-inflammatory effect on colonic LP in colitis mice, possibly due to the decreasing production of proinflammatory cytokines and inhibiting NLRP3 inflammasome signaling." (PMID 29888292, 2018). "In this study, we for the first time verified that formononetin could alleviate the DSS-induced acute colitis in mice by inhibiting NLRP3 pathway." (PMID 29507526, 2018). "However, the plant flavonoid alpinetin does improve DSS colitis through a similar mechanism of modulation of the NLRP3 and TLR4 pathways." (PMID 29515999, 2018). "Accumulating evidence support a pro-inflammatory contribution of NLRP3 to colitis pathology." (PMID 29872077, 2018). "Based on this background, the present study was designed to investigate how the direct blockade of NLRP3 with INF39 in experimental colitis compares, in terms of efficacy, with other drugs acting downstream (caspase-1 inhibition or IL-1β receptor blockade) on NLRP3 signaling." (PMID 30559669, 2018). "The NLRP3 inflammasome pathway was strongly related with treatment of TRAIL in acute colitis model." (PMID 29416724, 2018).
colitis (continued). "Through this study, we concluded that formononetin could protect colonic epithelial cells from injury to relieve the disease severity of colitis in mice via inhibition of NLRP3 inflammasome pathway." (PMID 29507526, 2018). "By contrast, a recent study by Zhou and colleagues showed that Nlrp3 inhibition by the flavonoid oroxylin A may have beneficial effects against colitis in DSS-treated mice." (PMID 29868004, 2018). "Our data therefore suggest that the manipulation of Cbl with hydrocotarnine to enhance NLRP3 inflammasome activation could be relevant for the treatment of infectious disease, colitis, and cancer." (PMID 30382081, 2018). "The macrophage cell in vitro data and colon explant data suggested that MCC950 effectively inhibited NLRP3 inflammasome assembly and may be key to controlling colitis." (PMID 29872077, 2018). "It follows from this that mice with PTPN22-deficiency manifest decreased NLRP3 inflammasome activity (and decreased IL-1β production) upon exposure to an inflammatory stimulus and therefore exhibit increased DSS-colitis in the same manner as do mice with frank NLRP3-deficiency." (PMID 30455704, 2018). "What’s more, colitis-associated adenomatous polyps were observed in Caspase1-deficient mice while absent in Nlrp3-deficient mice." (PMID 28360909, 2017). "Thus, DSS-induced acute and chronic colitis models were used here to evaluate the effect of oroxylin A on NLRP3 inflammasome." (PMID 28938606, 2017). "Although the role of NLRP3 in colitis is controversial, studies have demonstrated that NLRP3−/− mice develop less severe colitis than wild-type mice and that targeting the NLRP3 inflammasome can significantly ameliorate experimental colitis." (PMID 29354126, 2017). "However, in the context of DSS colitis models, the role of the NLRP3 inflammasome in IBD is still much debatable." (PMID 28553294, 2017). "However, we found that NLRP3−/− mice were significantly protected from DSS-induced colitis, showing a less severity of symptoms, including reduced DAI scores and colon shortening compared with WT mice." (PMID 28553294, 2017). "Current data allow to hypothesize that NLRP3 inflammasome can play both protective and detrimental roles in bowel inflammation, depending on the choice of colitis models and variations of commensal enteric microflora." (PMID 28179906, 2017). "The role of NLRP3 in colitis and colitis-induced gastrointestinal tumor has been ambivalent." (PMID 28938606, 2017). "Results from these studies show that mice deficient for inflammasome components, including NLRP3, caspase-1, NLRP1, NLRP6, and NLRC4, are highly susceptible to colitis-associated colon cancer induced by AOM/DSS by displaying severe intestinal inflammation, and increased number of colon polyps." (PMID 28955343, 2017). "We next explore whether celastrol inhibit DSS-induced colitis via inhibition of NLRP3 inflammasome activation." (PMID 28978034, 2017). "Furthermore, we found celastrol prohibited LPS-induced systemic inflammation and DSS-induced colitis via the inhibition of NLRP3 inflammasome activation in vivo." (PMID 28978034, 2017). "NLRP3 was the first reported inflammasome to protect against microbion-driven colitis, and NLRP3-deficient mice had increased susceptibility to experimental colitis, whereas in another study, mice lacking NLRP3 exhibited alleviative colitis severity." (PMID 28831399, 2017). "Therefore, NLRP3 inflammasome plays an important role in inflammatory injury repair stage of colitis and migration stage of gastrointestinal tumor." (PMID 28938606, 2017). "Consistent with in vitro data, procyanidin significantly downregulated MMP9, NF-κB, and NLRP3 inflammasome signaling pathway in DSS-induced colitis in mice, which might due in part to the decreased number of macrophages." (PMID 29354126, 2017).
colitis (continued). "In our previous work, we demonstrated that activation of cannabinoid receptor 2 could induce autophagy, which subsequently led to the inhibition of NLRP3 inflammasome in CNS in EAE as well as colitis mice models." (PMID 28559895, 2017). "Moreover, NLRP3 inflammasome has been reported to play an important role in colitis severity and inflammatory response in the DSS-induced model." (PMID 28938606, 2017). "In particular, treatment with wogonoside, a glucuronide metabolite of the bioactive flavonoid wogonin, reduced significantly colonic NF-κB and NLRP3 expression, as well as caspase-1 expression and activity in mice with colitis, exerting beneficial effects on colonic inflammation." (PMID 28179906, 2017). "Two initial reports showed that NLRP3 plays a key role in the regulation of intestinal homeostasis, maintaining the epithelial barrier integrity and reducing mortality during experimental colitis." (PMID 28179906, 2017). "We herein investigated whether celastrol can suppress DSS-induced colitis via inhibition of NLRP3 inflammasome activation." (PMID 28978034, 2017). "It is known that NLRP3 inflammasome plays a key role in the DSS-induced murine colitis." (PMID 28938606, 2017). "Our findings indicated that the NLRP3 inflammasome may play a critical role on DSS-induced colitis and its inhibition contributes to the anti-inflammatory effect of TER." (PMID 28553294, 2017). "Therefore, the in vivo pharmacological modulation of canonical NLRP3 inflammasome in more predictive animal models of colitis should be investigated, in order to clarify the role of this enzymatic complex in the pathophysiology of bowel inflammation." (PMID 28179906, 2017). "Therefore, although these findings are in contrast with previous observations, showing a protective role of NLRP3 during colitis, both highlight the relevance of NLRP3-enteric microbiota interplay in the maintenance of intestinal homeostasis." (PMID 28179906, 2017). "Here in our study, we observed that activation of CB2R could significantly promote autophagy process in macrophages, which in turn led to the inhibition of NLRP3 inflammasome activation in mice peritoneal macrophages and experimental colitis mice." (PMID 27611972, 2016). "In addition, we observed a positive correlation of the percentage of NLRP3 and cleaved caspase-1 double-stained cells with the severity of colitis (Matts’ grading score) in patients with UC." (PMID 27966619, 2016). "Our results showed that MALT1 inhibitors could suppress NLRP3 inflammasome activation in DSS-induced colitis model." (PMID 27105502, 2016). "The underlying mechanisms for the protective effect of MALT1 inhibitors in DSS-induced colitis may be attributed to its inhibition on NF-κB and NLRP3 inflammasome activation in macrophages." (PMID 27105502, 2016). "Furthermore, TRIM31 deficiency attenuates the severity of dextran sodium sulfate (DSS)-induced colitis, an inflammatory bowel diseases model in which NLRP3 possesses protective roles." (PMID 27929086, 2016). "In addition, studies in macrophages and mice models of IBD have uncovered the link between the abnormal activation of the NLRP3 inflammasome and colitis." (PMID 28119697, 2016). "However, several recent studies demonstrated that IL-18 derived from the NLRP3 inflammasome suppresses experimental colitis." (PMID 27966619, 2016). "In the present study, we examined the pharmacological effect of two specific MALT1 inhibitors MI-2 and mepazine on the dextran sulfate sodium (DSS)-induced experimental colitis in mice, followed by mechanistic analysis on NF-κB and NLRP3 inflammasome activation." (PMID 27105502, 2016). "Taken together, our data suggest that the loss of inflammasome signaling in myeloid cells may contribute to the increased sensitivity to DSS-induced colitis seen in Nlrp3−/− mice." (PMID 27610005, 2016).